ARID1B (AT-rich interaction domain 1B)
Diseases named in the same sentence as ARID1B in open-access papers (continued):
Sharing a sentence is not in itself a finding about the gene and the disease.
tumor (continued). "Given the absence of a second TSC2 variant, TSC2-LOH or any other evident tumor driver apart from the unclear variant in SIPA1L3 in the renal and hepatic AMLs of the herewith reported individual, a contribution of the germline ARID1B variant to the tumorigenesis cannot be excluded." (PMID 31077186, 2019). "Depletion of ARID1B may result in an overbalance of the tumor suppressing properties of ARID1A within the SWI/SNF complexes, resulting in decreased proliferation of un-irradiated cells with wild-type ARID1A." (PMID 31796878, 2019). "A univariate analysis showed that FIGO stage III/IV (p < 0.0001, log-rank test), CA125 level (p = 0.0088, log-rank test), residual tumor diameter ≥2 cm (p < 0.0001, log-rank test), and low ARID1B expression (p = 0.04, log-rank test) were correlated with shorter progression-free survival." (PMID 29890703, 2018). "Furthermore, Western blot analysis of SMOV2 tumor lysates demonstrated a significant reduction of ARID1B expression upon JQ1 treatment compared to DMSO vehicle control." (PMID 29760405, 2018). "Thus, upon prolonged exposure in an in vivo model, BET inhibition downregulates ARID1B, likely contributing to the enhanced sensitivity of these tumor xenografts to JQ1." (PMID 29760405, 2018). "Since depletion of Arid1b blunted the senescence response in vivo and resulted in higher percentages of proliferating Nras+ hepatocytes, we investigated whether the knockdown of Arid1b cooperated with NrasG12V in tumor formation." (PMID 27737960, 2016). "The downregulation in AML suggests a similar tumor suppressor function for ARID1B in blood." (PMID 25789315, 2015). "To further determine whether the nuclear localization of ARID1B is essential for its tumor‐promoting function, we performed a rescue experiment using ARID1B KO MDA‐MB‐468 cells stably expressing either ARID1B‐WT or nuclear localization‐deficient mutants M1 and M5." (PMID 40671262, 2025). "We first curated tumor-derived cell lines bearing intact expression of full-length ARID1A and ARID1B, those with loss of expression of ARID1A, and those characterized by dual-loss of ARID1A and ARID1B, isolated nuclear material and performed immunoblot analyses for mSWI/SNF family subunits." (PMID 41279405, 2025). "A possible contribution of the germline ARID1B variant to the tumorigenesis remains unclear but cannot be excluded given the absence of any other evident tumor drivers in the AMLs." (PMID 31077186, 2019). "Notably, accumulating evidence has drawn attention to the tumor suppressor role of ARID1B for HCC." (PMID 28415691, 2017). "Three patients with KRASMUT PDA achieved SD, of whom one had a tumor with ATM defects, and one had SWI/SNF complex alterations in PBRM1 and ARID1B genes." (PMID 40507311, 2025). "ARID1B negatively regulates ARID1A, impairing SWI/SNF‐mediated tumor suppression and enhancing tumor survival." (PMID 40671262, 2025). "To validate the role of ARID1B in tumorigenesis and drug response, we utilized preclinical mouse TNBC tumor models." (PMID 40671262, 2025). "In early stages or under homeostatic conditions, ARID1A and ARID1B, when functioning properly within the BAF complex, contribute to the suppression of tumor progression by regulating gene expression through chromatin remodeling." (PMID 40671262, 2025). "Together, these findings indicate that ARID1B OE can reduce ARID1A chromatin binding at select target genes, potentially contributing to oncogenesis by suppressing ARID1A tumor‐suppressive functions." (PMID 40671262, 2025). "It is entirely possible that ARID1B acts to repress β-catenin in a BRG1-dependent manner in peripheral blood lymphocytes and tumor cell lines and enhance β-catenin transcriptional activation in the developing brain." (PMID 33594090, 2021). "Since senescence is central to the tumor suppressor properties of SWI/SNF, we took advantage of the gained mechanistic insights explaining how ARID1B regulates senescence to target ARID1B-depleted cells." (PMID 27737960, 2016).
tumor (continued). "Treatment with the PARP inhibitor Niraparib significantly reduced tumor growth in the control group but not in the ARID1B OE group." (PMID 40671262, 2025). "Orthotopic injection into nude mice revealed that while ARID1B‐WT expression significantly restored tumor growth, neither M1 nor M5 mutant forms were able to rescue the ARID1B KO phenotype." (PMID 40671262, 2025). "Having demonstrated that ARID1B OE enhances tumor growth and confers resistance to PARP inhibition in vivo, we next investigated whether ARID1B nuclear localization is required for its tumor‐promoting function." (PMID 40671262, 2025). "The majority of DDEC/UEC harbor inactivating mutations involving core components of SWI/SNF complex with SMARCA4 and ARID1A/ARID1B being most commonly inactivated, resulting in absent expression of corresponding proteins in the undifferentiated tumor." (PMID 33125840, 2021). "Several subunits of the SWI/SNF complex including SNF5 (SMARCB1/INI1/BAF47), ARID1A (BAF240A), SMARCA4 (BRG1), ARID1B (BAF250B), ARID2 (BAF200) and PBRM1 (BAF180) exert critical tumor suppression activities, through inhibiting oncogenic transcription, cell cycle, epigenetic instability and etc.." (PMID 33670012, 2021). "The mRNA expression of ARID3A, ARID3B, ARID4B, JARID1B, JARID1C, JARID2 in tumor tissues was more expressive in normal tissues, ARID1B, ARID3C, ARID4A, ARID5A, ARID5B, JARID1A mRNA expression in tumor tissues were lower than that in the normal tissues (p<0.05)." (PMID 33592583, 2021). "Furthermore, there are only 3 and 2 exonic small deletions or insertions in cell line and primary tumor, respectively, including small insertions in both ARID1A and ARID1B genes." (PMID 33052929, 2020). "No further pathogenic variant in ARID1B, nor loss of heterozygosity (LOH) was observed in tumor tissues." (PMID 31077186, 2019). "In spite of a high frequency of ARID1B and ARID1A mutations in this series, only one tumour showed absence of expression of ARID1A." (PMID 30641862, 2019). "The remaining five mutation positive Group 1 tumours lacking a BRAF mutation possessed an FGFR1, NF1, ARID1B, HIST1H3B, and ATM mutations, respectively." (PMID 29058119, 2018). "In addition to recapitulating known alterations, MutComFocal identifies ARID1B, ROBO2 and MRS1 as candidate tumor suppressors and KLHL6, IL31 and LRP1 as putative oncogenes in DLBCL." (PMID 23531283, 2013). "Similarly, the IPS analysis showed a negative correlation between ARID1B expression and tumor immunogenicity." (PMID 38577613, 2024). "Although the results suggest that ARID1A and ARID1B may participate in the modulation of the TIME and are associated with the elevations in tumor mutability and PD-L1 expression, no molecular mechanism was explored in this research." (PMID 32791957, 2020). "They show that knockdown of the SWI/SNF component ARID1B prevents oncogene-induced senescence and cooperates with RAS to induce liver tumors, and their results provide new insights into the mechanisms by which epigenetic regulators can affect tumor progression." (PMID 27737960, 2016). "Interestingly, in ARID1B KO tumors, Ki67 expression was almost absent in the Niraparib‐treated group compared to the vehicle‐treated group, suggesting a significant reduction in tumor cell proliferation in response to the drug." (PMID 40671262, 2025). "Similarly, ARID1B, ARID2, JARID1C could function mainly as tumor suppressors in cancers." (PMID 33592583, 2021). "One tumor (IGR-03) diagnosed as SCCOHT did not exhibit a SMARCA4 mutation but instead, harbored concomitant and potentially biallelic loss-of-function alterations in two other SWI/SNF genes: ARID1A (two frameshifts—p.Q555fs and p.T1004fs) and ARID1B (stop gained R1944*)." (PMID 32575483, 2020). "Lastly, we established subcutaneous tumor models of the VOA1066 cell line (cell line xenograft (CDX)) and a novel PDX, XVOA14590, derived from a human DDEC primary tumor lacking both ARID1A and ARID1B expression." (PMID 41279405, 2025).
neurodevelopmental disorder (12 papers, 2016 to 2024). A behavioral and cognitive disorder with onset during the developmental period that involves impaired or aberrant development of intellectual, motor, or social functions. "De novo haploinsufficient mutations in the ARID1B gene cause severe neurodevelopmental disorders, which affect both physical and cognitive development." (PMID 34753942, 2021). "Therefore, Arid1b hKO mice represent a useful tool for advancing our understanding of the pathogenesis and underlying mechanisms of neurodevelopmental disorders." (PMID 28867767, 2017). "Mutations in several genes coding for chromatin remodelers and epigenetic modulators have been linked to neurodevelopmental disorders including ASD, with causative mutations identified in several chromatin remodelers (e.g. CHD8 and ARID1B)." (PMID 33350388, 2020). "This approach successfully identified fit-for-purpose candidate endpoints for ARID1B-related ID and possibly for other neurodevelopmental disorders." (PMID 32462407, 2020). "In this study, we investigate the syndrome ARID1B-related ID as a model to illustrate how to develop new biomarkers for a rare neurodevelopmental disorder." (PMID 32462407, 2020). "The aim of this study is to explore a novel approach towards developing new endpoints for neurodevelopmental disorders, in this case for ARID1B-related ID." (PMID 32462407, 2020). "This study shows that our approach towards the identification of fit-for-purpose endpoints in rare neurodevelopmental disorders has been successful in the case of ARID1B-related ID." (PMID 32462407, 2020). "Overall, it remains to be determined whether ARID1B’s functions in regulating cell proliferation or survival is likely to play a larger role in pathology of ARID1B-related neurodevelopmental disorders." (PMID 33594090, 2021). "AT-rich interactive domain 1B, ARID1B, and genes in the chromatin modification complex, SWItch/Sucrose Non-Fermentable (SWI/SNF), are thought to cause Coffin–Siris syndrome (CSS), an exceedingly rare neurodevelopmental disorder with fewer than 200 individuals diagnosed." (PMID 33757588, 2021). "Arid1b haploinsufficient mice demonstrate marked ID- and ASD-like characteristics, making them a useful mouse model for studying neurodevelopmental disorders." (PMID 33594090, 2021).
adenocarcinoma (4 papers, 2021 to 2022). A common cancer characterized by the presence of malignant glandular cells. "This study aimed to investigate the clinical relevance of immunohistochemical expression of proteins of the SWI/SNF complex, SMARCA2, SMARCA4 SMARCB1, ARID1A, ARID1B, and PBRM1 in 477 adenocarcinomas of the stomach and gastroesophageal junction." (PMID 34359794, 2021).
genetic disorder (3 papers, 2014 to 2024). "Interestingly, ARID1B is located at 6q25, an area of known loss of heterozygosity that has been linked to a documented genomic loss that drives inherited diseases of intellectual disability as well as multiple spinal meningiomas." (PMID 25774356, 2014). "This genetic disorder is caused by de novo mutations of ARID1A (CSS2; 1p36.11; MIM 614607), ARID1B (CSS1; 6q25.3; MIM 135900), DPF2 (CSS7; 11q13.1; MIM 618027), SMARCA4 (CSS4; 19p13.2; MIM 614609), SMARCB1 (CSS3; 22q11.23; MIM 614608) or SMARCE1 (CSS5; 17q21.2; MIM 616938) genes." (PMID 32916978, 2020). "Mutations in Coffin–Siris also occur in SMARCB1 (BAF47), SMARCA4 (BRG1), SMARCE1, ARID1A, and ARID1B, which attests to the role of the SWI/SNF complex in this genetic disorder." (PMID 25774356, 2014).
nail (1 paper, 2025). "We noted that ARID1B gene haploinsufficiency (proximal at Group C, 6q25.1) correlates with the distinctive nail hypoplasia/aplasia of the fifth finger." (PMID 41300817, 2025).
ARID1B also shares sentences with these, for which no sentence is quoted: Nicolaides-Baraitser syndrome (4 papers); breast tumor (3); Coffin-Siris syndrome 1 (3); cryptorchidism (3); psychiatric disorder (3); scoliosis (3); acute myeloid leukemia (2); Alzheimer disease (2); attention deficit-hyperactivity disorder (2); bladder urothelial carcinoma (2); congenital heart disease (2); infection (2); Kabuki syndrome (2); Kleefstra syndrome (2); language delay (2); prostate carcinoma (2); Seizure (2); Sleep apnea (2); thyroid cancer (2); acute lymphoblastic leukaemia (1); acute promyelocytic leukemia (1); ampullary carcinoma (1); anaplastic oligodendroglioma (1); angiomyolipoma (1); Astigmatism (1); astrocytoma (1); brain disorder (1); carcinoids (1); carcinosarcoma (1); cervical adenocarcinoma (1).
A further 73 diseases each share a sentence with ARID1B in 1 paper.